F9 (coagulation factor IX)
Diseases named in the same sentence as F9 in open-access papers (continued):
Sharing a sentence is not in itself a finding about the gene and the disease.
colitis (1 paper, 2018). Inflammation of the colon. "In case of DSS-induced colitis, F9-deficiency reduces the extent of the acute intestinal inflammation." (PMID 29945876, 2018). "To our knowledge, we are the first to show that the anti-hemophilic clotting factor IX is present in intestinal epithelial cells and F9-deficiency rendered protection against colitis." (PMID 29945876, 2018). "Here, we reveal in a dextran sulfate sodium (DSS) mouse model of acute intestinal inflammation, that F9-deficiency is protective against colitis." (PMID 29945876, 2018). "In the 3.5% DSS-colitis mouse model, F9-deficiency protected from weight loss and reduced colon length." (PMID 29945876, 2018). "Collectively, our results demonstrate that F9-deficiency protects against DSS-induced colitis." (PMID 29945876, 2018). "Thus, we revealed a protective role of F9-deficiency in DSS-induced colitis and identified the intestinal epithelium as a site of ectopic FIX." (PMID 29945876, 2018).
colon tumour (1 paper, 2020). "PEGylation makes F9 suitable for passive targeting due to a prolonged blood circulation profile by evading the immune system thus maximising its accumulation in colon tumour mass and minimising its unnecessary biodistribution to other body organs after i.v. administration." (PMID 32239473, 2020).
dengue (1 paper, 2025). "Coagulation factor IX detection reflects ongoing coagulopathy, which is consistent with dengue-induced platelet aggregation, endothelial tissue factor expression, and coagulation cascade activation." (PMID 41583452, 2025).
gestational diabetes mellitus (1 paper, 2025). "Similarly, in studies of gestational diabetes mellitus (GDM), proteomic techniques such as mass spectrometry have revealed several potential urinary biomarkers such as coagulation factor IX and the trans-α-trypsin inhibitor heavy chain H4 (ITIH4)." (PMID 40149657, 2025).
glioma (1 paper, 2020). A benign or malignant brain and spinal cord tumor that arises from glial cells (astrocytes, oligodendrocytes, ependymal cells). "Additionally, six targets are regulated by our miRNAs both in glioma and meningioma: CR2, KNG1, PROS1, F9, MBL2 and F11, while different miRNAs are dysregulated in each cancer type." (PMID 32545233, 2020).
osteoporosis (1 paper, 2022). A condition of reduced bone mass, with decreased cortical thickness and a decrease in the number and size of the trabeculae of cancellous bone (but normal chemical composition), resulting in increased fracture incidence. "Furthermore, 7 key genes associated with osteoporosis treatment drugs were screened and found to be negatively correlated with CD45+ BM-MSCs_5 subgroup score, and they showed excellent diagnosis efficiency, especially F9 gene." (PMID 36199280, 2022). "Through network pharmacology, we found that DB03742 is highly bound to F9 protein, which is a potential F9 protein inhibitor, and speculated that DB03742 may be effective in the treatment of osteoporosis." (PMID 36199280, 2022).
prostate carcinoma (1 paper, 2022). A carcinoma that arises from epithelial cells of the prostate gland. "We found that F9 is upregulated in the tumour stroma in comparison with healthy stroma in breast and colon, but not in prostate cancer." (PMID 35184131, 2022).
rhegmatogenous retinal detachment (1 paper, 2023). Retinal detachment secondary to retinal tear or break. "Both were found upregulated in rhegmatogenous retinal detachment (RRD) compared to ERM, while coagulation factor IX (F9) and complement components C8 chain (C8) and C2 were found down-regulated." (PMID 36875133, 2023).
infection (14 papers, 2011 to 2025). The state of being infected such as from the introduction of a foreign agent such as serum, vaccine, antigenic substance or organism. "The encoding gene of coagulation factor IX was significantly up-regulated under both of the JDm10/HN10 infections." (PMID 35893682, 2022). "For coagulation factors, coagulation factor IX was significantly increased under the HN10 infection." (PMID 35893682, 2022). "The hexon hypervariable region-7 (HVR-7) of HAdV-C5 and HAdV-A31 interacts with human coagulation factor IX and X, which bridge virions to cellular heparan sulfate, resulting in enhanced infection of target cells." (PMID 32376620, 2020). "Real-time PCR assays of F9 gene expression in Lenti-X HEK293 and human mesenchymal cells models revealed elevated amounts of mRNA after 24 h of culture post-infection." (PMID 39768347, 2024). "For the serine protease system, coagulation factor IX, three chains of fibrinogen, and complements C8, C5, and C2s were significantly up-regulated by the HN10 infection, suggesting that the serine protease-mediated immune system might be involved in the resistance to NDRV infection." (PMID 35893682, 2022). "FREP 2 and 3, coagulation factor IX, dermatopontin, dual oxidase, galectin 4, MIF, peroxiredoxin, superoxide dismutase Cu-Zn, and heat-shock protein 70 all exhibited increased expression in snails that successfully resisted infection compared to those that were infected by S. mansoni." (PMID 22479663, 2012).
cancer (10 papers, 2019 to 2025). A tumor composed of atypical neoplastic, often pleomorphic cells that invade other tissues. "Recently, coagulation factor IX was implicated as a regulator of senescence in cancer cells and inhibition of coagulation factor Xa induced plaque regression and increased plaque stability." (PMID 37097759, 2023). "To further determine if there is a wider implication for F9 loss-of-function in other types of cancers, we tested a panel of 22 cancer cell lines from different origins and molecular characteristics with increasing concentrations of Palbo, Abema and Ribo." (PMID 35184131, 2022). "Our data suggest that increased levels of F9 upon the induction of senescence maintain certain cancer cells in a stable cell cycle arrest, while F9 loss-of-function promotes a proliferative advantage." (PMID 35184131, 2022). "Altogether, our data highlight a partial relevance for F9 mRNA expression in other cancer cell lines." (PMID 35184131, 2022). "Finally, we screened a panel of 22 cancer cell lines for their response to different CDK4/6 inhibitors and we show that F9 loss-of-function confers a partial resistance to the proliferative arrest induced by CDK4/6 inhibitors in other tumour types." (PMID 35184131, 2022). "Importantly, we unveiled a correlation between the levels of F9 and cancer progression studying different cancer-related datasets." (PMID 35184131, 2022). "Importantly, bioinformatics analysis of cancer datasets suggest a role for F9 in human tumours." (PMID 35184131, 2022). "However, FCN3, SLC22A1, ADH4, CYP2C8, SLC10A1, F9, and FBP1 were significantly downregulated in HCC tissue compared to the matched para-carcinoma tissue." (PMID 38664521, 2024). "Meanwhile, treatment with recombinant F9 induced a senescence-like proliferative arrest in MCF7 cells but not in cancer cells which did not upregulate F9 upon Palbo treatment." (PMID 35184131, 2022).
tumor (4 papers, 2022 to 2025). "Analyses of published datasets suggest a role for F9 in carcinogenesis in different tumours in humans." (PMID 35184131, 2022). "In addition, we have found that PBK may promote tumor proliferation through angiogenesis and F9 may be a predictor of tumor immunotherapy response." (PMID 36685860, 2022). "While F9 knockout prevents the induction of senescence, treatment with recombinant FIX halted the cell cycle and a senescence-like state in MCF7 tumor cells." (PMID 40725041, 2025). "While F9 knockout prevents the induction of senescence, treatment with a recombinant F9 protein was sufficient to induce a cell cycle arrest and senescence-like state in MCF7 tumour cells." (PMID 35184131, 2022).
inflammation (1 paper, 2018). Aberrant reaction of the microcirculation characterized by movement of fluid and leukocytes from the blood into extravascular tissues. "As the prevalence of IBD was found to be reduced in hemophilic patients, we were curious to explore whether coagulation factor IX-deficient (F9−/−) C57BL/6 mice are protected against 3.5% DSS-induced acute intestinal inflammation." (PMID 29945876, 2018).
F9 also shares sentences with these, for which no sentence is quoted: bleeding disorders (31 papers); coagulation disorder (7); genetic disease (6); Stroke (5); X-linked disease (4); anaphylaxis (3); diabetes (3); endothelial dysfunction (3); factor deficiency (3); metabolic syndrome (3); venous thromboembolism (3); acute myocardial infarction (2); Arthritis (2); blood disorder (2); cardiovascular disease (2); Hunter syndrome (2); Lupus (2); Obesity (2); abscess (1); acholinesterasemia (1); acquired hemophilia (1); amyloidosis (1); Antithrombin deficiency (1); Apert syndrome (1); arterial disease (1); atrial septal defect (1); co-infection (1); colorectal adenocarcinoma (1); congenital hypopituitarism (1); Cushing syndrome (1).
A further 47 diseases each share a sentence with F9 in 1 paper.